SMAD4 (SMAD family member 4)
Diseases named in the same sentence as SMAD4 in open-access papers (continued):
Sharing a sentence is not in itself a finding about the gene and the disease.
cancer (continued). "Smad4 ChIP-Seq was performed in whole epithelium in mouse, and in CaCo2 and SW480 cancer cell lines." (PMID 38136364, 2023). "Together with two Reactome pathways (SMAD4 MH2 Domain Mutants in Cancer and SMAD2/3 MH2 Domain Mutants in Cancer), two KEGG pathways were related to pathways in cancer." (PMID 36959830, 2023). "We found that a number of signaling networks and their components such as PI3K/Akt/mTOR, MMP‐2 and 9, Wnt/‐catenin, PARP, MAPK, NF‐κB, Caspase‐3/8/9, Bax, Bcl2, Smad4, Notch1, STAT3, Nrf2, and ROS signaling can be regulated in cancer cells by phytochemicals." (PMID 37132286, 2023). "However, it is also conceivable that Prdm16 might function to suppress metastasis induced by other TGF-β superfamily members, such as Activins and BMPs, which are known to signal through Smad4, and can enhance malignancy and promote cancer metastasis in a variety of human malignancies." (PMID 36828547, 2023). "SMAD4 expression and Tgfβ inhibitors in CRC cell lines limit cancer cell migration, thus suppressing metastatic progression." (PMID 38136364, 2023). "ChIP-seq Enrichment Analysis (ChEA) for these up-regulated genes in the KO cells demonstrated over-representation of transcription factors of SUZ12, AR, Nrf2, SMAD4, as well as SOX2 and Nanog important for the stem cells and cancer stem cells." (PMID 37151890, 2023). "These miRNAs bind directly to PAK3, blocking its production, and thus SMAD4 deletion activates the PAK3-JNK-Jun pathway, which in turn accelerates cancer metastasis." (PMID 37685308, 2023). "Mice induced to lose SMAD4 and simultaneously activate BRAFV600E/+ in the gastrointestinal tract develop serrated tumors, which can efficiently advance to invasive carcinomas." (PMID 38136364, 2023). "Our analysis of the SMAD4 mutations in these patients using the same primer pairs as those used in the Cancer Hotspot Panel did not identify any germline mutations; however, we are currently discussing whether patients should be tested for germline mutations in genetic counseling." (PMID 35928693, 2022). "Although all the designed drugs utilize the HYAL-2/WWOX/SMAD4 signaling to control cancer growth, it is necessary to compare the efficacy of HAson8, Zfra4-10, WWOX7-21 and other available drugs in treating cancer in vivo." (PMID 35883580, 2022). "SENP2 facilitates TGF-β-Smad4 signaling pathway by desumoylating Smad4 at lys159 to promote EMT and cell migration in TNBC cells and sustain cancer stem cell properties." (PMID 35216622, 2022). "The stronger the binding, the weaker the cancer growth, suggesting that Zfra4-10 or WWOX7-21 peptide-induced HYAL-2/WWOX/SMAD4 signaling is involved in the increased binding of WWOX with its partners." (PMID 35883580, 2022). "Compared with other molecules directly downstream of ALK, such as Smad4, STAT3, PI3K and PLC-γ, TOPK is a better target for cancer therapy." (PMID 36167821, 2022). "ARID1A and SMAD4, which annotated deletions in the TCGA STAD cohort, were inferred to be deleted in the cancer cell cluster." (PMID 35087207, 2022). "Among these 13 PD-L1 enhancers, except for the two cancer drivers (PAN3 and SMAD4), 11 of the enhancers belong to druggable genes." (PMID 36357569, 2022). "A previous study for cancer genome map research shows that 13% of LSCC and 47% of LAC have Smad4 deletion." (PMID 33794845, 2021). "However, in some cancer types, SMAD4 is neither mutated nor deleted." (PMID 34070531, 2021). "The present study aimed to determine if miR-362 targeted and regulated expression of SMAD4 and the TGF-β/SMAD signaling pathway to modulate migration and invasion of cancer cells." (PMID 33746597, 2021). "Therefore, SMAD4 expression could be potentially used as a molecular marker for cancer resistance." (PMID 34048444, 2021). "SMAD4 and NF1, the known cancer-related genes in the CGC database, are the common ceRNAs of NEAT1 in all six CCNs." (PMID 33987091, 2021).
cancer (continued). "Therefore, if non-mutated functional components of the TGF-β signaling pathway (e.g. TGF-β receptor type II and SMAD4) are indeed transported by CAFs-exosomes to cancer cells, the TGF-β signaling pathway could be reactivated, contributing to cancer progression and metastasis in this context." (PMID 34852849, 2021). "Highly significant expression changes in 17 known cancer genes such as ERBB2, KRAS and SMAD4 were observed by analyzing the RNA sequencing data of 116 EACs, showing a correlation with a high degree of chromosomal instability." (PMID 34503107, 2021). "Among these SMAD4 is a downstream mediator of transforming growth factor beta (TGF-β) that regulates cell proliferation of CSCs, differentiation, apoptosis and cancer progression." (PMID 34803458, 2021). "Among the cancer genes involving cell motility, PAK3 was the top DEG after ablation of Smad4 (SPK vs. PK)." (PMID 34381046, 2021). "The results showed that the positive expression rate of Smad4 in NSCLC tissues was 48.1% (25/52), while the positive expression rate in normal cancer-adjacent lung tissues was 73.1% (38/52)." (PMID 33794845, 2021). "The expression level of Smad4 in the serum and cancer tissues of NSCLC patients is decreased and the decreased Smad4 is related to poorly differentiated cancer, lymphatic metastasis and advanced TNM staging." (PMID 33794845, 2021). "SIRT7 seems to have a dual role in cancer cells by targeting substrates (e.g., H3K18ac, ATM, and SMAD4)." (PMID 32404984, 2020). "Given the multiple roles of TGFβ in cancer and its impact on PDAC, it seems interesting to focus on its effector SMAD4." (PMID 32429474, 2020). "Five TFs, SUZ12, SMAD4, REST, EZH2 and NFE2L2, were found to be enriched in all four cancers, suggesting that transcriptional dysregulation of tumors with aberrant AMPK signaling involved direct physical associations of these TFs with target DEGs." (PMID 32807122, 2020). "Such being the case, Wnt5A, CTNNB1P1, SMAD4, and TCF4 was expressed primarily in the para-cancer tissues but were reduced to varying degrees in cancer tissues." (PMID 32273945, 2020). "In pancreatic intraepithelial neoplasia, AGR2 acts as a SMAD4-suppressible gene that regulates MUC1 levels and stimulates the initiation and progression of cancer." (PMID 32322663, 2020). "SMAD4, is a key signaling protein in the TGF-β pathway, and plays a controversial role in the development of cancer; however, it is known that the number of SMAD4 mutations correlates with patient prognosis." (PMID 33036243, 2020). "In line with our expected, miR-455 was found to be significantly up-regulated, but SMAD4 and CDKN1B were significantly down-regulated in cancer." (PMID 31763681, 2020). "As a member of the SMAD family, SMAD2 plays a key role, together with SMAD3 and SMAD4, in TGF-β signaling and cancer progression." (PMID 31762811, 2019). "This pan-cancer analysis also indicated that SMAD4 gene alterations occurred most frequently in PDAC, compared with other cancer types." (PMID 31569425, 2019). "The knockout of SMAD4 partially conferred BMP ligand resistance to the anti-growth effects in hepatocellular carcinoma cells, which reduced the cells formation and migratory ability." (PMID 30745456, 2019).
cancer (continued). "These four pathways were proteoglycans in cancer (ANK2, FASLG, HSPG2, PTPN11, STAT3, and VEGFA), HIF-1 signaling (ARNT, STAT3, and VEGFA), FoxO signaling (FASLG, SMAD4, and STAT3), and ECM-receptor interaction (HSPG2 and LAMA2)." (PMID 29300322, 2018). "In addition, APC and SMAD4 mutations have not been reported in this subtype of cancer either." (PMID 29133385, 2018). "High molecular weight HA increases the formation of endogenous Hyal-2/WWOX/Smad4 complex rapidly, followed by relocating to the nuclei in 20-40 min, in WWOX-expressing normal and cancer cells." (PMID 27845895, 2017). "Genes that contribute to the positive regulation of transcription from RNA polymerase II promoter including SMAD family member 4 and ISL LIM homeobox 1 were both down regulated in cancer cells treated with L6 or L7 tomato extract." (PMID 28448505, 2017). "For hub PCGs, CCND1 and SMAD4 are cancer driver genes that mediated cell cycle and TGF-β signaling which are all cancer development related biological processes." (PMID 27580177, 2016). "In addition, mutations in non-MSI cancers may occur in their common downstream signaling component SMAD4." (PMID 26497569, 2015). "TGF-β, by inducing formation of NF1/Smad4 complex, inhibits ANT2 in cancer cells, and this repression of ANT2 contributes to senescence-associated oxidative stress and DNA damage." (PMID 26078812, 2015). "After verifying the biological meaning of the low-cost paths, the signal TGFβ1- TGFβR1- SMAD2/3- SMAD4- AR-OCIAD2 was discovered and explained TGFβ's stimulation on OCIAD2 expression in cancer." (PMID 24949437, 2014). "According to the immunostaining results, the expressions of p21 were clearly elevated in the cancer cells of patients with wild-type ACVR1B and SMAD4 genes, compared with the expression levels in patients with the homozygous deletion of the ACVR1B gene." (PMID 24886203, 2014). "Smad4 is a critical regulator of transforming growth factor (TGF)-β signaling and is defective in numerous human cancers." (PMID 24944686, 2014). "We found two major types of complexes that are affected by miRNAs during cancer progression; the first contains SMAD3, SMAD2, SMAD4, SMAD6, FOXO1, HOXC8, and SKIL, which are connected to AKT1, which is in turn a key modulator of TGF-B signaling pathway." (PMID 24391925, 2013). "In the present study, real-time RT-PCR revealed significantly increased mRNA expression of TGF-β in patients with carcinoma derived from branch duct-type IPMN, and patients expressing SMAD4 had significantly worse outcomes." (PMID 23833648, 2013). "In addition, intragenic mutation and loss of heterozygosity (LOH) at the Smad4 locus has been reported in many tumors, although these genetic alterations may not directly cause inactivation of Smad4 in some cancers." (PMID 22204491, 2011).
cancer (continued). "Mutations in two Smad family member genes - SMAD4 (also known as MADH4, DPC4 &JIP) and SMAD2 (also known MADR2, and hMAD-2) have been identified in human cancers and more importantly with high frequency in pancreatic and CRCs." (PMID 20565773, 2010). "miR-34a-5p in order to cancer proliferation regulation, inhibits TGF-β1/Smad4 signaling pathway." (PMID 40061926, 2025). "Other miRNAs, such as the miR-17-92 cluster, have been shown to target SMAD4 and C-MYC in different cancers, suggesting that multiple miRNAs may cooperatively regulate the same pathway." (PMID 40224178, 2025). "SMAD4 gene inactivation is also common in PDAC and promotes tumor progression by inducing epithelial-to-mesenchymal transition (EMT), which confers migratory and invasive properties to cancer cells." (PMID 40918466, 2025). "During cancer progression, transforming growth factor-β (TGF-β) sequentially activates SMAD2/3 and SMAD4 through activation of TGF-β type I receptor (TβRI), and SMAD4 enters the nucleus and promotes the expression of oncogenes, leading to epithelial-mesenchymal transition (EMT)." (PMID 41050073, 2025). "Studies have reported that miR-27a and miR-155 target SMAD2 and SMAD4, which may lead to downregulation of TGF-β1 in some cancers, which is important for modulating the antitumor effects of the pathway in early-stage tumors." (PMID 40943648, 2025). "Notably, Patient 63 had a KRAS G12V, SMAD4, GNAS, and KMT2C mutant-positive PDAC with liver metastases while Patient 64′s cancer was BRAF V600E-positive, and they had also undergone treatment with experimental BRAF and MEK inhibitors." (PMID 39941724, 2025). "In Smad4-positive cancer cells, KLF5 is downregulated and Sox4, in the absence of KLF5, induces apoptosis by upregulating pro-apoptotic factors." (PMID 38569937, 2024). "SMAD4’s role as a central mediator in the TGF-β signaling pathway, regulating key cellular processes such as proliferation, differentiation, and apoptosis, is well-documented, with its involvement in cancer highlighting its potential as a therapeutic target." (PMID 38975339, 2024). "Moreover, LINC00909 inversely regulated SMAD4 expression, knock-down of SMAD4 rescued the effect of LINC00909-deletion inhibition on pluripotency factors and cancer stem cells phenotype." (PMID 38504385, 2024). "Interestingly, enforced expression of BMP4 resulted in a trend of increased AKT1 phosphorylation in both SMAD4-expressing and SMAD4-knockdown cells, consistent with previous reports of a similar effect by BMP2 in other cancers." (PMID 38689334, 2024). "This meta-analysis aimed to assess the impact of the most relevant molecular alterations in cancer-related genes of CRC (i.e., RAS, BRAF, SMAD4, PIK3CA) as prognostic markers of survival and disease recurrence in patients with mCRC surgically treated by LM resection." (PMID 39220128, 2024). "Furthermore, SMAD4 plays a pivotal role in the regulation of Epithelial-Mesenchymal Transition (EMT), a process with implications for cancer growth, wound healing and cancer metastasis." (PMID 38666907, 2024). "SMAD4 regulates EMT through the TGF-beta signaling pathway, thereby suppressing cancer cells." (PMID 39113194, 2024). "SMAD4 is considered an important mediator of TGF-β signaling and may be a potential therapeutic target for cancer treatment." (PMID 38461536, 2024). "SMAD4 is required for the function of TGF-β signaling pathway and related to carcinoma metastasis." (PMID 39593114, 2024). "If suppression of proliferation is not the immediate impact of SMAD4 expression, then how does SMAD4 directly impede cancer invasion?" (PMID 38136364, 2023).
cancer (continued). "The authors further demonstrated that RUNX3 responded to and interacted with SMAD4 status to regulate the balance between cancer cell division and dissemination, and they suggested that RUNX3 and SMAD4 levels can be used together to inform clinical decision-making for resectable PDAC." (PMID 37596627, 2023). "In the presence of SMAD4 deletion, pathways other than TGF/SMAD would work in cancer promotion." (PMID 36088360, 2022). "MiR-130a inhibits Smad4 expression by binding directly to the 3′UTR of Smad4 at the miRNA consensus sites of miR-34a, miR-146a, and miR-199a, which are also the negative regulators of Smad4 in cancer progression." (PMID 35682652, 2022). "One such difference is in the mutation rate of tumor suppressor SMAD4, which showed a higher prevalence in double mutant cancers in TCGA but not in the DFCI cohort, where all four groups had similar SMAD4 mutation rates." (PMID 36079062, 2022). "Our previous studies demonstrated high SMAD4 and N-cadherin staining at the invasion front in resected BTC specimens and suggested that EMT may be induced at the cancer invasion front." (PMID 36088360, 2022). "In this perspective review article, we detail the molecular action of WWOX in the HYAL-2/WWOX/SMAD4 signaling for biological effects, and discuss WWOX phosphorylation forms in interacting with binding partners, leading to suppression of cancer growth and retardation of AD progression." (PMID 35883580, 2022). "Smad4 protein was exclusively localised in the epithelial nuclei and the expression in normal tissues was comparable between the FFPE and fresh samples, anatomical sites, and cancer stages." (PMID 34867090, 2021). "SMAD4 is a member of the SMAD family and participates in the transforming growth factor-β (TGF-β) pathway, which inhibits the activity of normal immune cells and promotes the immune escape of cancer cells." (PMID 34616403, 2021). "Nevertheless, in the Human Protein Altas, there are no evident difference in SMAD4 expression between cancer cell lines and normal cell lines." (PMID 35008475, 2021). "Taking these together, FAM83 members may regulate or be regulated by KRAS or SMAD4 in PDAC, leading to cancer progression." (PMID 33747255, 2021). "In EOC cells, SMAD4 and PTEN (phosphatase and tensin homolog) genes have been identified as miR-205 targets, and their downregulation contributes to cell proliferation, migration, and cancer cell invasion." (PMID 34721577, 2021). "In a few cancer types, promoter hypermethylation of the SMAD4 gene has been recorded but does not appear to be a common event in carcinogenesis." (PMID 33825073, 2021). "Hence, miR-362 both negatively and positively regulates SMAD4 expression in TGF-β/SMAD signaling pathway to suppress cell motility and invasiveness and metastasis, and may explain the reported clinical association of anti-miR-362 with suppressed metastasis in various cancers." (PMID 33746597, 2021). "Low levels of these factors do not favor the growth of cancer cells, whereas high expression level of SMAD4 correlated with favorable OS." (PMID 34138687, 2021). "The TGF-β/SMAD4 signaling pathway, which interacts with other classical pathways, such as MAPK, PI3K/AKT, and WNT/β-catenin, can influence cancer initiation and progression through multiple mechanisms, such as apoptosis, DNA damage repair and epithelial-mesenchymal transition." (PMID 33117720, 2020). "Loss of SMAD4 induces constitutive activation of STAT3 in pancreatic cancer, which cooperates with non-canonical TGF-β signaling to promote cancer progression." (PMID 31952344, 2020).